IL22 (interleukin 22)
Diseases named in the same sentence as IL22 in open-access papers (continued):
Sharing a sentence is not in itself a finding about the gene and the disease.
infection (continued). "After 60 h of infection, at the more acute phase, the bacteria had induced a substantial increase in the expression of genes for most proinflammatory cytokines, including IFN-γ, IL-1β, IL-2, IL-6, IL-8, IL-22, and TNF-α, as well as genes for IL-10 and IL-4." (PMID 27357336, 2016). "Following infection of differentiated THP-1 macrophages with an adherent and invasive C. concisus strain, genes encoding IL-23 and IL-18, but not IL-22, were regulated as assessed by transcriptomic and proteomic analyses." (PMID 27385977, 2016). "Although in TNFα-deficient mice lung infiltrating cells showed an increased granulocytic CD11b+Ly6G+ cell response, the absence of IL-17RA and/or IL-22 had little influence on CD11b+Ly6G+ cells one month post-infection." (PMID 27853279, 2016). "Even at higher infection doses, the combined absence of the IL-17RA and IL-22 pathways did not profoundly compromise the control of chronic M. tuberculosis infection, which argues against major compensation between the two pathways in this model." (PMID 27853279, 2016). "In accordance with an unaltered pathology, survival rates were not influenced by the absence of IL-22 after infection with 50 parasites." (PMID 27650379, 2016). "While a pathologic and inflammatory role for IL-22 has been reported in other cutaneous diseases, we found that IL-22 does not promote increased inflammation during infection with Leishmania spp." (PMID 26285207, 2015). "If IL-22 is absent during initial infection by C. rodentium, IL-22 does not provide adequate protection against the bacteria." (PMID 26793707, 2015). "Since IL-22 can be produced by several cell types, including T lymphocytes and innate lymphoid cells, we compared its expression during infection in mice lacking T cells (Tcr-β-/-) and C57BL/6 mice." (PMID 26285214, 2015). "Recently, it was reported that IL-22 does not play a role during a low dose of infection with L. major." (PMID 26285207, 2015). "This may reflect the overall levels of IL-22 produced by ILC versus Th22 cells, or alternatively the localization of these cells during the course of infection." (PMID 26285214, 2015). "IL-22 is known to have a relationship with virus-infection reactions and whose receptor is confined to non-hematopoietic cells (mainly epithelial cells)." (PMID 26474968, 2015). "While IL-22 production is increased after infection with Listeria monocytogenes, it is not required for clearance of the infection." (PMID 25799189, 2015). "By modulating IL-22 expression, IFN-α may undermine bacterial clearance in an early-phase of infection." (PMID 26152778, 2015). "Compared to uninfected controls at day 7, infection of non-Tg mice with C. albicans significantly (p < 0.05) enhanced tongue tissue expression of S100a8, Ccl20, Il17, Il22 and, to a lesser degree, of the Dfb3 gene." (PMID 25344377, 2014). "IL-22 also upregulates expression of the inflammatory chemokines CXCL1, CXCL2, and CXCL5, which act in synergy with IL-17 to induce a chemotactic environment that promotes neutrophilia at sites of infection." (PMID 24586147, 2014). "IL-22+ (and IL-22−) NK cells upregulated the activation marker CD69 upon infection." (PMID 24721575, 2014). "As seen in the experiments with T cells from healthy control individuals, memory CD4+ T cells from patients with CF produce significant amounts of IL-17A, IL-22 and IFN-γ in response to DC infection with either laboratory or clinical PA strains compared with uninfected DCs." (PMID 24587305, 2014). "Furthermore, T cells produce IL-22 in certain infections, and codepletion of CD4+ and CD8+ cells (which includes CD4+ NK T cells) also reduced IL-22 production." (PMID 24721575, 2014). "In contrast to the reported properties of peripheral blood derived Th22 cells without a characterised antigen specificity, IL-22 production in response to PA infection was from memory CD4+ T cells that did not express the skin-homing receptors CCR4 or CCR10." (PMID 24587305, 2014).
infection (continued). "To evaluate whether IL-22 is required for protective immune responses after high dose Mtb infection, we infected mice with more than 1000 CFU Mtb and followed the course of infection." (PMID 23460846, 2013). "In contrast, the ω-3 PUFA supplemented group was unable to induce such responses during infection evident by the lack of induction of IFN-γ, TNF-α, IL-17A, IL-22 and IL-23, as well as the chemokine Relm-β compared to pre-infection expression." (PMID 23405155, 2013). "However, at day 254 of infection, Mtb-specific IL-17A-producing CD4+ T cells were significantly enhanced in IL-22−/− mice." (PMID 23460846, 2013). "So far we have shown that after low dose infection with Mtb IL-22 is not essential for the efficient generation of inflammatory immune responses and the subsequent induction of antigen-specific TH1 and TH17 cells." (PMID 23460846, 2013). "The levels of myeloperoxidase (as neutrophil marker), TNFα, INFγ, GM-CSF, IL-1β and IL-6 transiently increased in lungs after infection, while levels of IL-10, IL-17A and IL-22 were indistinguishable from PBS controls." (PMID 22319619, 2012). "On day 14 post infection, compared with those in control mice treated with PBS only, much higher levels of the IL-22 protein and gene transcripts were detected in myocardium in AVMC mice, respectively (236.24 ± 43.26 vs. 17.45 ± 5.21, 21.28 ± 4.28 vs. 4.28 ± 0.97, both p<0.01)." (PMID 23050732, 2012). "Our findings suggest that IL-22 is not required for clearance of LM during primary or secondary infection, using both systemic and mucosal models of infection." (PMID 21347242, 2011). "The factors elevated included A-SAA, a protein primarily synthesized by cells in the liver, high-level production of which is known to be induced during the acute phase response to infection, trauma or stress by pro-inflammatory cytokines including TNF-alpha, IL-6 and IL-22." (PMID 20463814, 2010). "The immune regulatory factors regulating T cells actively producing IL-22 during infections have not been studied." (PMID 20195465, 2010). "Against our initial assumption, AhrdCAIR/dCAIR mice showed no defects during this infection and dealt with it more efficiently than wildtype mice, exhibiting lower bacterial levels, less inflammation and increased production of IL-22, a major determinant of barrier protection in this infection." (PMID 40502009, 2025). "Il22−/− mice, with or without FT, displayed induction of IL-17A, IL-17F, and IL-10 upon infection." (PMID 41361166, 2025). "Moreover, Il22-/- mice showed no changes in number or proportion of ILC2s upon CR infection compared to uninfected controls." (PMID 40591723, 2025). "Unexpectedly, because of the higher fungemia observed on the absence of IL-22, the IL-22−/− mice exhibited the lowest lung fungal burden on the third week of infection, that could be explained by the greater yeast evasion through the airway-blood barrier." (PMID 39635124, 2024). "However, at later stages of infection, CD4+ T cells in the crypts emerge as the major sources of IL-22, as demonstrated by studies using CD4CreIl22flox/flox mice, which specifically lack Il22 in T cells." (PMID 39379604, 2024). "However, only in the absence of IL-22 the frequencies of infiltrating macrophages and neutrophils kept higher late in the infection, suggesting more innate immune response in terms of cell frequency in the lungs." (PMID 39635124, 2024). "Furthermore, a more inflammatory lung microenvironment is induced during the infection in the absence of IL-22 cytokine." (PMID 39635124, 2024). "The infection outcome in S100a9−/− mice closely resembled that of WT mice, indicating that C. rodentium is resistant to calprotectin and that S100a9−/− mice do not phenocopy the survival impairment observed in Il22−/− mice." (PMID 38557196, 2024). "However, the primary source of IL-22-producing cells during the infection was predominantly Tγδ lymphocytes and non-lymphoid cells." (PMID 39635124, 2024).
infection (continued). "Interestingly after evaluating the IL-22 source contribution in the lung microenvironment, we described that in the present mice model, the major source of IL-22 during the infection are γδ T cells and non-lymphoid cells." (PMID 39635124, 2024). "No change in IL-22 was observed post-infection with C. perfringens." (PMID 38164397, 2023). "Confirming our published results, the current data also demonstrated that, during experimental infection with S. mansoni, there is an activation of Th2 and Th17 responses, regardless of the absence of the IL-33 receptor; however, the IL-22 levels decreased systemically and locally." (PMID 37373379, 2023). "Interestingly, Krt5-immunoreactive pods observed in lungs of either IL-22 LOF or IL-22r cLOF mice 14 days post-PR8 infection displayed evidence for Scgb3a2 expression that was absent in comparable Krt5-immunoreactive pod structures of wildtype control mice." (PMID 37726288, 2023). "By using a mouse model of excisional cutaneous wounds co-infected or not with S. aureus and P. aeruginosa, we show that the infection specifically increases the expression of IL-17A, IL-17F and IL-22, and that these cytokines are responsible for the delayed wound healing observed in infected wounds." (PMID 36275755, 2022). "Of the proinflammatory cytokines assayed, IL-22 was noteworthy in that it was significantly elevated in IFT88 KO mice relative to IFT88 control mice in both the uninfected and Mabs-infected groups, suggesting an important role for this cytokine in our infection model." (PMID 36505420, 2022). "Indeed, whereas IL-1b protein accumulation was not impacted by the absence of lymphocytes and was up-regulated by PAO1 infection (Figure 3C1), IL-23 and IL-22 were down-regulated by PAO1 treatment (Figure 3C2,C3)." (PMID 35955566, 2022). "Furthermore, the cytokines induced by stimulation of cells extracted from the skin with HK S. aureus, namely IL-17A, IL-22, GM-CSF, IFN-γ, and TNF-β, were induced also by epicutaneous infection of human skin with live S. aureus, strengthening the value of this in vitro model." (PMID 33796109, 2021). "Exposure to PM resulted in an immediate (0.5–1-day post-exposure; dpe) increase in IL22 expression in the lungs of C57BL/6 neonatal mice; however, this IL22 expression was not maintained and failed to increase with either continued exposure to PM or subsequent Flu infection of PM-exposed mice." (PMID 34906172, 2021). "Finally, we are not aware of reports that have measured Fas-ligand and IL-22 on serum or plasma linking their levels to type of infection, and therefore this study is the first, to our knowledge, to report their potential relevancy." (PMID 34263738, 2021). "Moreover, in IL22-treated organoids we observed mostly single MHV-GFP expressing cells, whereas in the untreated organoids most MHV-GFP-positive cells were clustered, suggesting that IL22 suppresses the infection of neighboring cells." (PMID 34045640, 2021). "IL-22 and IFN-λ therefore have many shared characteristics and there is a growing body of evidence that signaling of these two cytokines are intimately related in regulating not only the local inflammatory environment in response to infection but also the strength of the airway epithelial barrier." (PMID 32637365, 2020). "We do not know precisely which cells produce IL-17A/F and IL-22 in the MG during infection." (PMID 33059767, 2020). "However, others did not observe an increase in IL-22 following exogenous IFNλ delivery in a similar super-infection model." (PMID 32582219, 2020). "Ifn-γ and il-22 were not different between D+ WT, D- WT and D-Cyp KO mice at d14 post-infection." (PMID 30723466, 2019). "Indeed, we found that IL-22 mRNA and protein expression was impaired in these mice as opposed to wild-type mice in infection." (PMID 31681274, 2019).
infection (continued). "Expression of an array of cytokines (CSF3 [G-CSF], IFNγ, IL-1β, IL-6, IL-22, IL-17A, and IL-10), chemokines (CCL20, CXCL2 and CXCL9) and receptors (CD40) known to be involved in the regulation of S. pneumoniae inflammatory response was measured at 0, 6, 24, and 48 h post-infection." (PMID 30333823, 2018). "At first sight, the production of IL-22 was not determinant for the outcome of infection." (PMID 30045763, 2018). "Collectively, H9N2 AIV infection enhanced the expression of proinflammatory cytokines, such as IFN-α, IL-17A, IFN-γ, and IL-22, and promoted the proliferation and translocation of Proteobacteria, especially E. coli, which might be induced by the injury of mucous layers and tight junctions." (PMID 29783653, 2018). "It is important to note that even though the abundance of the IL-22 regulated antimicrobial proteins is reduced following infection with ΔespO, the residual levels are sufficient to mediate bacterial clearance (albeit delayed), unlike il-22 KO mice which succumbed to C. rodentium infection." (PMID 30365535, 2018). "In addition, levels of il17a and il22, transcripts that code for TH17 cytokines were higher in lungs from stat3fl/fllysm cre mice than in those from littermate controls when measured at 4 and 8 weeks after infection." (PMID 29338039, 2018). "This suggests the promotion of IL-22 production by ILC3 was independent of infection." (PMID 28701769, 2017). "Interestingly, the production of IL-22 but not IL-17 from ILC3 was similarly enhanced by PFOS treatment without infection." (PMID 28701769, 2017). "In vivo neutralisation of IL-22 prior to infection did not affect pulmonary bacteria loads." (PMID 28887540, 2017). "Compared to the infection status where an extensive pro-inflammatory cytokine production from both ILC3 and Th17 cells was induced in PFOS treated mice, only the induction of IL-22 from ILC3 and Th17 cells was consistently found in PFOS treated group under the steady state." (PMID 28701769, 2017). "In addition, it has been reported that IL-22 neutralization for 1 day did not alter AST levels in Clone 13 infection at 22 dpi47." (PMID 28634408, 2017). "In addition to this phenotype an early increase of IFNγ and an overall lower IL-17 production was observed in the absence of IL-22 during PbA infection." (PMID 27311945, 2016). "However, the surprising role of IL-22 for ILF formation was only observed after infection with C. rodentium, but not during the steady state." (PMID 27656182, 2016). "Our data suggest that IL-22 induced by orally fed BLS-mix not only acts on the intestine to maintain the mucosal homeostasis, it also promotes an inflammatory response in inflamed intestinal mucosal tissues as a result of infection with enteropathogenic bacteria." (PMID 27424033, 2016). "However, this seems to be independent on CXCL9, as we found an unaltered CXCL9 secretion by the lack of IL-22 during infection." (PMID 27650379, 2016). "Having demonstrated that IL-22 could be produced locally in response to pulmonary P. aeruginosa infection, we compared the response to infection in wild-type mice and animals lacking the ability to produce IL-22." (PMID 27375092, 2016). "However, IL-22−/− mice seemed to be more efficient in clearing the parasites as no trypomastigotes were detectable at day 27 post infection in IL-22−/− mice, whereas C57BL/6 mice exhibited detectable numbers of parasites until day 43 post infection." (PMID 27650379, 2016). "Furthermore, the authors concluded that IL-22 is the only indispensable cytokine necessary to ensure host defense against C. rodentium during the early stages of the infection as opposed to IL-17A, IL-17F, IL-19, IL-20, and IL-24." (PMID 26793707, 2015).
infection (continued). "Infection of IL-6-deficient mice led to profound defects in lamina-propria-resident TH22 cell numbers, but not IL-22 production from other cells, relative to IL-23-deficient mice or WT counterparts, illustrating the importance of IL-6 in regulating TH22 differentiation." (PMID 24586147, 2014). "Focusing on IL-22, our detailed analysis revealed that after infection with Mtb IL-22 has no influence on the expression of inflammatory cytokines, cellular infiltration, the expansion of memory T cells, the development of TH1 and TH17, and the expression of macrophage effector functions." (PMID 23460846, 2013). "Subsequent to Th17 cell activation, an increase in IL-17 production at the early stages of infection may benefit the infected host by (i) inducing chemokines (IL8/CXCL8) that recruit neutrophils and (ii) promoting IL-22 mediated production of defensins at the site of infection." (PMID 24073293, 2013). "To address these questions, we isolated lymphocytes from BAL fluid, and right caudal lung lobe (infection site), spleen and mesentery lymph nodes obtained from the M. tuberculosis-infected macaques, and measured T cells actively producing IL-17 or IL-22 without in vitro antigen re-stimulation." (PMID 20195465, 2010). "In this infection model, ILC1s but not ILC3s make a major contribution to host resistance; loss of IFN-γ or T-bet-expressing ILC1s in Rag1−/− mice are susceptible to C. difficile infection, while loss of ILC3s or IL-22 production has a limited impact on the recovery following C. difficile infection." (PMID 35163778, 2022). "Whether or not the different expression levels of cytokines, such as IFNs, IL22, IL17, which were induced by NDV infection, account for differences in gut microbiota alteration and clinical symptoms post different virulent NDV strain infection needs further study." (PMID 36230299, 2022). "Moreover, production of IL-22 by ILC3s is required for protective immunity towards pathobionts, such as Citrobacter rodentium, since mice lacking ILC3s or IL-22 quickly succumb to the infection." (PMID 32429359, 2020). "Moreover, we did not observe increased expression of CXCL1, one of the chemokines known to recruit neutrophils to the lamina propria soon after infection, in Citrobacter dosed animals regardless of the diet, suggesting that IL-22 was upregulated via a different pathway." (PMID 32082288, 2020). "Furthermore, HPX reduced the level of infection (judged by decreased numbers of circulating bacteria) in IL22−/− mice regardless of whether it was from an intravenous or oral infection." (PMID 31554244, 2019). "While we previously reported no global difference in total neutrophil numbers within inflamed tissue during infection with WT or ΔespO, supporting our IL-22 expression data, neutrophil distribution within the inflamed colon was not assessed and could be altered after infection with ΔespO." (PMID 30365535, 2018). "In animal models, the absence of these cytokines (IL-22) may lead to sensitivity to infection." (PMID 29318122, 2018). "However, such anti-microbial factors may be induced by alternative non-IL-22 pathways, including via IL-17, and thus may further explain our observed lack of impact of IL-22 on bacterial burden or infection rates in persistent PA infection." (PMID 27375092, 2016). "Notably, relatively high expression of IL22 mRNA by rabbit PBMCs following in vivo infection of the animals may help explain that no viral RNA was detected in their PBMCs at 3-day pi." (PMID 26697438, 2015). "Interestingly, a significant induction (8 to 28 fold) of IL-22, IL-17A and IL-17F was also observed for the avirulent strain, while induction of the eight next most expressed cytokines during infection with the virulent strain were either not induced or induced weakly (<2-fold)." (PMID 22675469, 2012).